USP25 (ubiquitin specific peptidase 25)
Diseases named in the same sentence as USP25 in open-access papers (continued):
Sharing a sentence is not in itself a finding about the gene and the disease.
ischemic stroke (1 paper, 2023). A stroke disorder caused by obstruction of blood flow to the brain, due to thrombotic (local blood clot formation) or embolic (due to a blood clot or other material traveling from another site) event. "Here, it is found that deficiency of the ubiquitin‐specific protease USP25 significantly aggravate ischemic stroke injury in mice." (PMID 37587766, 2023). "In the present study, we demonstrated that ischemic stroke injury was ameliorated by the deubiquitinating enzyme USP25, which reduced neuronal loss and neurological deficits by inhibiting microglia‐mediated inflammatory responses." (PMID 37587766, 2023). "Given that USP25 is a DUB that participates in the regulation of various inflammatory diseases and that neuroinflammation is also a critical factor underlying ischemic stroke injury, we asked whether USP25 was involved in ischemic stroke injury." (PMID 37587766, 2023). "Consistently, we found that USP25 deficiency aggravated MCAO‐induced neuronal damage, as protein levels of NeuN and PSD95 were significantly lower in infarcted brains of USP25−/‐ mice as compared with that in WT mice after ischemic stroke." (PMID 37587766, 2023). "In both mouse and human brains, USP25 is markedly upregulated in microglia in the ischemic penumbra, implying a clinical relevance of USP25 in ischemic stroke." (PMID 37587766, 2023). "AAV9‐mediated TAB2 knockdown ameliorates ischemic stroke injury and abolishes the effect of USP25 deletion." (PMID 37587766, 2023). "Collectively, these results show that USP25 deficiency increases MCAO‐induced infarct volume, neuronal damage, and neurological deficits in mice, indicating a protective role of USP25 in ischemic stroke injury." (PMID 37587766, 2023). "Ablation of USP25 significantly enlarged the infarct volume on day 3 and 7 after reperfusion, suggesting that USP25 alleviates cerebral injury induced by ischemic stroke." (PMID 37587766, 2023). "Higher percentages and absolute numbers of infiltrating macrophages, which are key players in ischemic stroke, were detected in injured hemispheres of USP25−/− mice." (PMID 37587766, 2023). "Our experimental data show that USP25 is a key inhibitor of ischemic stroke injury, indicating that therapeutic augmentation of USP25 function might be beneficial for the treatment of ischemic stroke." (PMID 37587766, 2023). "USP25 has no impact on neuronal death under hypoxic conditions, but reduced ischemic stroke‐induced neuronal loss and neurological deficits by inhibiting microglia‐mediated neuroinflammation." (PMID 37587766, 2023). "USP25 is upregulated in microglia in both humans and mice after ischemic stroke." (PMID 37587766, 2023). "Thus, USP25 serves as a new and potent inhibitor of neuroinflammation after ischemic stroke, providing a novel therapeutic target for treating ischemic stroke." (PMID 37587766, 2023). "Interestingly, we found that USP25 was also upregulated in peri‐infarct microglia in patients with ischemic stroke." (PMID 37587766, 2023). "Moreover, a compensatory upregulation of USP25 was observed in microglia after ischemic stroke in both mice and humans." (PMID 37587766, 2023). "Interestingly, USP25 expression was markedly upregulated in microglia in the brains of patients with ischemic stroke." (PMID 37587766, 2023). "Collectively, USP25 is identified as a critical inhibitor of ischemic stroke injury and this data suggest USP25 may serve as a therapeutic target for ischemic stroke." (PMID 37587766, 2023). "Therefore, USP25 may serve as a potential therapeutic target for ischemic stroke." (PMID 37587766, 2023). "Together, these results show that USP25 is upregulated in microglia in response to the stress of ischemic stroke, probably serving as a negative‐feedback mechanism to inhibit the activation of microglia." (PMID 37587766, 2023).
liver diseases (1 paper, 2023). "Since the anti-oxidation function of NRF2 is beneficial in a large number of disease settings including neurological and liver diseases, our finding here opens the door for future exploration and application of USP25 inhibitors for various disease conditions." (PMID 37339955, 2023).
liver fibrosis (1 paper, 2025). "Collectively, USP25 deficiency can protect against liver fibrosis." (PMID 39781451, 2025). "To further determine the correlation between USP25-mediated tissue fibrosis and M2 macrophage polarization, we next tested M2 macrophage polarization related indicators in pulmonary and liver fibrosis models." (PMID 39781451, 2025). "To further confirm the effect of USP25 on tissue repair and fibrosis, we established a mouse liver fibrosis model by BDL for 14 days." (PMID 39781451, 2025). "Pathological results showed that the degree of liver fibrosis in USP25-/- mice was significantly reduced compared to WT mice." (PMID 39781451, 2025). "In our study, we delved into the role of USP25 in tissue fibrosis by establishing pulmonary fibrosis models and liver fibrosis models in USP25 knockout (USP25-/-) mice." (PMID 39781451, 2025). "In the liver fibrosis model, we extracted hepatic macrophages for flow cytometry and found that the proportion of M2 macrophages of USP25-/- mice was significantly lower than that of WT mice." (PMID 39781451, 2025). "In this study, we found that ubiquitin specific peptidases 25 (USP25) deficiency could protect mice from bleomycin (BLM)-induced pulmonary fibrosis and bile duct ligation (BDL)-induced liver fibrosis." (PMID 39781451, 2025). "Next, we examined USP25 expression in the lungs following BLM-induced pulmonary fibrosis and in the livers following BDL-induced liver fibrosis in animal models." (PMID 39781451, 2025). "Our study revealed that the deletion of USP25 can inhibit the STAT6/PPAR-γ signaling pathway by enhancing the ubiquitination of STAT6, thereby affecting macrophage M2 polarization, ultimately alleviating BLM-induced pulmonary fibrosis and bile duct ligation-induced liver fibrosis." (PMID 39781451, 2025). "In this study, we found that the absence of USP25 improved pulmonary and liver fibrosis in mice." (PMID 39781451, 2025).
lung adenocarcinoma (1 paper, 2019). A carcinoma that arises from the lung and is characterized by the presence of malignant glandular epithelial cells. "RPL3, HSP90AA1, ATAD2, and PIAS1 as well as USP25, which is targeted by miR-200b, miR-200c, and miR-429, may be the potential targets of HPD in lung adenocarcinoma." (PMID 30717818, 2019). "RPL3, HSP90AA1, ATAD2, as well as PIAS1 and USP25, which is targeted by miR-200b, miR-200c, and miR-429 may show correlations with the sensibilization effect of HPD in lung adenocarcinoma." (PMID 30717818, 2019).
Lymphatic Metastasis (1 paper, 2014). Transfer of a neoplasm from its primary site to lymph nodes or to distant parts of the body by way of the lymphatic system. "Further analysis showed that USP25 levels were significantly higher in NSCLC patients with lymphatic metastasis than in those without lymphatic metastasis (P < 0.0001)." (PMID 24997798, 2014).
metastatic tumors (1 paper, 2014). "In contrast, few metastatic tumors were detected in mice injected with SPC-A-1sci-sh-USP25 cells." (PMID 24997798, 2014).
myocardial infarct (1 paper, 2025). "TTC/Evan Blue staining found that USP25 deficiency led to a more severe myocardial infarct area induced by I/R." (PMID 39985261, 2025). "TTC/Evan Blue staining assay showed the reduced myocardial infarction area in I/R‐treated USP25oe mice, indicating that cardiomyocyte‐specific USP25 overexpression significantly ameliorated myocardial I/R injury." (PMID 39985261, 2025).
myocardial ischemia (1 paper, 2025). A disorder of cardiac function caused by insufficient blood flow to the muscle tissue of the heart. "Moreover, deubiquitinating enzyme USP25 improves myocardial ischemia-reperfusion injury by deubiquitinating NLRP3 and negatively regulating the activity of the NLRP3 inflammasome in cardiomyocytes." (PMID 40413536, 2025).
nephritis (1 paper, 2024). Inflammation of renal tissue. "While the role of USP25 has been extensively studied in various immune-related contexts, its function in nephritis remains unexplored." (PMID 38616174, 2024). "USP25-deficient anti-GBM GN mice were generated, and their nephritis progression was monitored." (PMID 38616174, 2024).
osteoporosis (1 paper, 2021). A condition of reduced bone mass, with decreased cortical thickness and a decrease in the number and size of the trabeculae of cancellous bone (but normal chemical composition), resulting in increased fracture incidence. "Our results reveal that the ubiquitin-specific protease family may play important roles in menopause and that USP25 is related to osteoporosis pathogenesis." (PMID 35141233, 2021).
Ovarian cyst (1 paper, 2021). The presence of one or more cysts of the ovary. "Regarding the morphology of the ovaries, the ovaries of both the USP25+/+ and USP25–/– control mice had follicles at various stages of development with surrounding theca cells (TC), GCs, and corpus luteum (CL), and neither structural anomalies nor ovarian cysts were discovered." (PMID 34805185, 2021).
pancreatic adenocarcinoma (1 paper, 2020). "Pancreatic adenocarcinoma shows the strongest upregulation of USP25 expression in tumors with a high EGFR expression, and this prompted us to evaluate cancer patient survival." (PMID 33202887, 2020).
primary brain tumors (1 paper, 2023). "We identified a selected group of DUBs (USP13, USP14, USP19, USP25, OTUD2/YOD1) associated with the Regulation of ERAD pathway across several adult and pediatric primary brain tumors (GBM, EPN, CPh, MB)." (PMID 37892185, 2023).
prostate carcinoma (1 paper, 2024). A carcinoma that arises from epithelial cells of the prostate gland. "USP25 is known to interact with TNKS, influencing prostate cancer cell proliferation via the WNT signaling pathway, which plays a crucial role in PCa progression." (PMID 38321455, 2024).
pulmonary fibrosis (1 paper, 2025). Chronic progressive interstitial lung disorder characterized by the replacement of the lung tissue by connective tissue, leading to progressive dyspnea, respiratory failure, or right heart failure. "The lower Ashcroft score also demonstrated a significant reduction in the lung fibrosis in USP25-/- mice." (PMID 39781451, 2025). "In a pulmonary fibrosis model, Western blot and RT-qPCR analysis found that expression of M2-labeled Arg1 in USP25-/- mice was significantly reduced compared to WT mice." (PMID 39781451, 2025). "Next, levels of IL-4, IL-13 and TGF-β1 in BALF of WT and USP25-/-mice after BLM-induced pulmonary fibrosis models were measured by ELISA." (PMID 39781451, 2025).
renal carcinoma (1 paper, 2022). A carcinoma arising from the epithelium of the renal parenchyma or the renal pelvis. "Under normoxic conditions, constitutively high protein levels of HIF-1α in the pVHL-deficient renal carcinoma cell line RCC-4 were unaffected by depletion of USP25." (PMID 35440539, 2022).
steatosis (1 paper, 2024). Increased lipid within the cytoplasm of cells. "Intriguingly, when primary mouse hepatocytes were exposed to free fatty acids (FFAs) to induce steatosis, Usp25 protein levels were significantly lower than those in hepatocytes treated with bovine serum albumin." (PMID 39395794, 2024). "Similarly, knocking down USP25 in Huh7 cell lines aggravated FFA-induced steatosis, whereas USP25 overexpression ameliorated FFA-induced steatosis in Huh7 cell lines." (PMID 39395794, 2024). "Finally, a USP25 inhibitor exacerbated diet-induced steatosis in mice." (PMID 39395794, 2024).
Stroke (1 paper, 2023). Sudden impairment of blood flow to a part of the brain due to occlusion or rupture of an artery to the brain. "In mice, knockout of USP25 increases microglia‐mediated neuroinflammation and thereby significantly exacerbates stroke‐induced neurological deficit." (PMID 37587766, 2023). "It is possible that USP25 may directly regulate neuronal death after stroke." (PMID 37587766, 2023).
systemic lupus erythematosus (1 paper, 2024). An autoimmune multi-organ disease typically associated with vasculopathy and autoantibody production. "Additionally, we explored USP25 expression in kidney tissue from a mouse model of spontaneous systemic lupus erythematosus (MRL/MpJ-Faslpr/J mice)." (PMID 38616174, 2024).
cancer (23 papers, 2014 to 2026). A tumor composed of atypical neoplastic, often pleomorphic cells that invade other tissues. "Disruptions of the proteasome system via alterations of USP25 activity have been associated with various human cancers." (PMID 34249948, 2021). "Previous studies provided evidence that elevated levels of USP25 are linked to the progression of different cancer types such as non-small-cell lung carcinoma (NSCLC), which are characterized by EGFR genetic alterations and aberrant EGFR signaling." (PMID 33202887, 2020). "To establish the clinical relevance of our findings, we took advantage of publicly available cancer patient databases and analyzed the mRNA expression levels of USP25 and how they are linked to EGFR." (PMID 33202887, 2020). "Notably, aberrant expression of ubiquitin specific peptidase 25 (USP25) has been reported to be associated with poor prognosis in various cancer types and evidence suggests that it promotes tumor growth, metastasis, and the chemotherapeutic response." (PMID 41326342, 2025). "USP25 is closely linked with malignant tumors, immune responses, and inflammation." (PMID 35450028, 2022). "Furthermore, the activation of USP25 in vitro and in vivo is achieved through mutations associated with cancer, suggesting a functional link between the auto-inhibitory and pro-cancer effects." (PMID 34249948, 2021). "USP25 has been associated with inflammation, immune response, and cancer." (PMID 30478318, 2018). "Interestingly, one of the known fusion partners of ALDH1A3 is USP25, a ubiquitin-dependent protease, which localizes in both nucleus and cytoplasm and has been implicated as a tumor-promoting factor in different types of human cancers." (PMID 35052687, 2021). "USP25 and USP28 are critical deubiquitylases (DUBs) that have been implicated in various diseases, particularly cancer and cardiac dysfunction." (PMID 42017948, 2026). "Inhibiting USP25 can increase the sensitivity of cancer cells to chemotherapy drugs such as IR, 5-Fu, and cisplatin." (PMID 41321637, 2025). "The opposite trend was observed in MDSCs cocultured with USP25 overexpressing cancer cells, and the administration of IL-6 reversed this trend." (PMID 41326342, 2025). "We further show that USP25 inhibitors we have discovered are capable of destabilizing KRAS in cancer cells and are efficacious in blocking tumor xenograft growth in mice." (PMID 40473213, 2025). "To explore the role of USP25 in cancer cell proliferation, we performed colony formation and CCK8 assays." (PMID 41321637, 2025). "Depleting USP25 expression in cancer cells increases ubiquitination and proteasomal degradation of KRAS, leading to the suppression of its downstream MAP kinase pathway and cell proliferation." (PMID 40473213, 2025). "For instance, in pancreatic cancer, USP25 stabilizes HIF1α through deubiquitination, thereby promoting glycolysis in cancer cells and consequently driving tumor progression." (PMID 40607251, 2025). "Together, these data strongly support the notion that USP25 promotes cancer cell growth, through (at least partly) stabilizing KRAS expression." (PMID 40473213, 2025). "IHC results showed significant downregulation of USP25 expression in carcinoma tissue compared with normal tissue." (PMID 41326342, 2025). "USP25 and USP28, which are highly homologous and associated with diseases like cancer and neurodegenerative disorders, have recently become focal points for the development of therapeutic inhibitors." (PMID 39678489, 2024). "While USP25 has important roles in cancer, it similarly plays a critical part in other diseases, including diabetes and metabolic diseases of muscle and adipocytes." (PMID 34249948, 2021). "It is known that USP25 is involved in the metastasis of non-small celllung cancer cells, which is promoted by inducing miR-200C." (PMID 29658970, 2018).